WDR26 (WD repeat domain 26)
Diseases named in the same sentence as WDR26 in open-access papers (continued):
Sharing a sentence is not in itself a finding about the gene and the disease.
congenital heart disease (1 paper, 2021). A heart disease that is present at birth. "One novel fame-shift deletion (c.550_556delCCTTTAG/p.P184Cfs*9) in the WDR26 gene was detected in an infant with absence seizures and febrile seizures, ventriculomegaly, intellectual/developmental disabilities, congenital heart disease, facial dysmorphism, and yellow hair." (PMID 34055682, 2021).
developmental disabilities (1 paper, 2021). "As WDR26 is located in chromosomal region 1q42, this showed that the patient shared some clinical features with 1q41q42 microdeletion syndrome, such as seizures, intellectual/developmental disabilities, and facial dysmorphism." (PMID 34055682, 2021).
infarction (1 paper, 2020). A localised pathological necrosis of tissue resulting from obstruction of the blood supply usually by a thrombus, an embolus, or vascular torsion. "Wdr26 was shown to be downregulated in the rat infarction model, while its candidate regulator, miR-550b-2-5p, was upregulated in this study, consistent with the inhibition model of miRNAs." (PMID 32354168, 2020).
invasive ductal carcinoma (1 paper, 2020). "Interestingly, we found that the cellular localization of WDR26 was mainly nuclear in normal breast tissue and lobular hyperplasia, while in the advanced phases of the disease (i.e. DCIS and invasive ductal carcinoma samples) WDR26 localization was almost exclusively cytoplasmic." (PMID 33056990, 2020).
leukemia (1 paper, 2016). A malignant (clonal) hematologic disorder, involving hematopoietic stem cells and characterized by the presence of primitive or atypical myeloid or lymphoid cells in the bone marrow and the blood. "Previously, we reported that in leukemia cells, WDR26 fosters the interaction between Gβγ and its effector PLCβ2 by directly binding both proteins, thereby promoting Gβγ-stimulated PLCβ2 activation and Ca2+ signaling." (PMID 26895380, 2016). "In leukemia cells, we first showed WDR26 is required for chemokine-induced cell migration." (PMID 26895380, 2016).
tauopathies (1 paper, 2025). "Notably, the PLA positive signal in tauopathies was less frequent than that observed in AD, supporting our co-IP results that suggested a stronger interaction between WDR26 and tau in AD than in tauopathies." (PMID 40317322, 2025). "Further exploration of WDR26 and the CTLH E3 ubiquitin ligase are important to determine if this complex is involved in tau clearance in AD, and if this role is limited to AD or also occurs in other tauopathies." (PMID 40317322, 2025). "There were observable but faint evidence of an interaction between tau and WDR26 in PiD and PSP, but not CBD, suggesting WDR26 may interact with tau in select primary tauopathies in addition to AD." (PMID 40317322, 2025).
cancer (5 papers, 2016 to 2024). A tumor composed of atypical neoplastic, often pleomorphic cells that invade other tissues. "In conclusion, by utilizing mouse models of a broad array of aggressive cancers and by performing a pan-cancer analysis, we have identified biomarkers associated with cancer progression: two TAp63-regulated oncogenic lncRNAs or TROLLs and one of their common interacting proteins, WDR26." (PMID 33056990, 2020). "To further evaluate the role of PTPN21 or WDR26 in cancer development, we used a xenograft model to assess the in vivo effects of inhibiting these genes." (PMID 39872503, 2024). "Our data indicate that WDR26 is upregulated in malignant cancer tissues and its expression strongly correlates with poor patient survival." (PMID 26895380, 2016). "WDR26 was upregulated in multiple cancers to promote tumor progression." (PMID 35897048, 2022). "Given the correlation between high expression of TROLL-2 and TROLL-3 and the cytoplasmic localization of WDR26 in invasive human cancers, we hypothesised that these two lncRNAs may promote the cytoplasmic localization of WDR26 to promote metastasis." (PMID 33056990, 2020). "We next asked whether expression of TROLL-2 and TROLL-3 correlated with cytoplasmic WDR26 more broadly across other aggressive human cancers by performing a pan-cancer analysis." (PMID 33056990, 2020). "Next, we used a pan-cancer approach to determine whether TROLL-2 and TROLL-3 activated AKT through WDR26 in a broader cancer context." (PMID 33056990, 2020). "We note that our study complements work by the Luis Parada laboratory describing similar effects of YPEL5 and WDR26 deletion in mouse cells on NMNAT1 amounts, and on modulating the efficacy of a candidate prodrug in the killing of specific types of cancer cells (personal communication)." (PMID 38759627, 2024). "Given this context, we explored whether WDR26, important in mitochondrial stress-induced ISR, impacted the anchorage-independent growth of cancer cells." (PMID 39872503, 2024). "On the contrary, WDR26-ΔNES showed no appreciable difference in migration or invasion compared to cells treated with empty vector, indicating that cytoplasmic WDR26, but not nuclear WDR26, functions downstream of TROLL-2 and TROLL-3 and plays a crucial role in cancer progression." (PMID 33056990, 2020).
tumor (5 papers, 2016 to 2022). "In a seperate study, WDR26 was shown to stablise the Akt signaling complex to promote tumour cell growth and metastasis." (PMID 30323900, 2018). "In addition, given that WDR26 is prognostically important in basal-like tumours with high expression of TROLL-3, we verified whether these factors may also be prognostic in other tumour types." (PMID 33056990, 2020). "In highly malignant cell lines (MDA-MB231, DU4475 and BT549), downregulation of WDR26 expression selectively alleviated GPCR- but not EGF receptor-stimulated PI3K/AKT signaling and tumor cell growth, migration and invasion." (PMID 26895380, 2016). "In addition, downregulation of WDR26 in highly malignant cell lines alleviated GPCR-stimulated PI3-kinase/AKT signaling, tumor cell growth, migration, and invasion but did not alleviate EGF receptor-stimulated PI3-kinase/AKT signaling and tumor cell growth, migration, and invasion." (PMID 31885576, 2019).
WDR26 also shares sentences with these, for which no sentence is quoted: developmental delay (3 papers); neurodevelopmental disorder (3); adenocarcinoma (1); anemia (1); blood cancer (1); colon cancer (1); genetic disorder (1); intellectual disability syndrome (1); lung adenocarcinoma (1); lung carcinoma (1); lung squamous cell carcinoma (1); metastatic cancers (1); metastatic tumors (1); oral diseases (1); ovarian carcinoma (1); Pick disease (1); Seizure (1); serous adenocarcinoma (1); squamous cell carcinoma (1); Ventriculomegaly (1).